CGAS (cyclic GMP-AMP synthase)
Diseases named in the same sentence as CGAS in open-access papers (continued):
Sharing a sentence is not in itself a finding about the gene and the disease.
cancer (continued). "A study on early neoplastic progression demonstrated that after cGAS binds to cytosolic dsDNA in cancer cells, the cGAS–STING pathway mediates the secretion of type-I IFN to elicit a robust immune response and recruits immune cells to inhibit tumorigenesis in a cancer cell-autonomous manner." (PMID 37686127, 2023). "Inhibition of the cGAS-STING pathway may facilitate the escape of cancer cells from immunosurveillance." (PMID 36926349, 2023). "cGAS is a direct cytosolic double-stranded DNA (dsDNA) sensor crucial for activating the type I interferon response to invading DNA viruses or bacteria; however, it also plays an important role in cancer development." (PMID 37444620, 2023). "Moreover, cancer treatments that include radiotherapy and chemotherapy which induce DNA damage and genomic instability also showed the ability to activate the cGAS–STING pathway and the development of antitumor immune responses." (PMID 37560754, 2023). "Combining temozolomide (a chemotherapeutic agent) and CD47 blocking agents, including antagonistic anti-CD47 monoclonal antibody (mAb) increases type 1 IFN production by activating cGAS/STING signaling in myeloid antigen-presenting cells (APCs)/MICs in different cancers." (PMID 37380989, 2023). "In all, our study demonstrated that m6A and m5C modification of GPX4 may be a promising target for cancer immunotherapy via activating the cGAS-STING signaling pathway in COAD." (PMID 38065948, 2023). "We show here that at very low doses the Taxane Paclitaxel (Pxl) indeed induces a potent proinflammatory response in various cancer cell types in a cyclic GMP-AMP (cGAMP) synthase (cGAS)- and Stimulator of Interferon Genes (STING)-dependent manner, leading to interferon (IFN) signaling." (PMID 36960066, 2023). "However, it is important to consider the increase in solute DNA levels in cancer cells with high chromosomal instability (CIN) which can lead to endogenous cGAS/STING activation." (PMID 37781382, 2023). "Other critical questions, such as how multiple innate DNA sensors activate the context-dependent response programs and crosstalk with each other and how the cGAS-STING pathway communicates with cancer-specific metabolism and nutrients, are intriguing questions remaining to be answered." (PMID 36861445, 2023). "Research into the cGAS-STING pathway has undoubtedly expanded the potential for cancer treatment." (PMID 37448962, 2023). "In specific cancer cell lines, the promoters of cGAS and STING are prone to undergo loss-of-function mutation or epigenetic silencing, which leads to the suppression of the cGAS–STING pathway." (PMID 37686127, 2023). "G3BP1, encoding the core components of stress granules, promoted DNA binding and activation of cGAS pathway, might unfold an unknown vision between microbe and cancer." (PMID 37917664, 2023). "Extranuclear DNA has been shown to play an important role in tumors through increased oncogene expression, genetic heterogeneity between cancer cells, and resistance to therapy.The presence of double-stranded DNA (dsDNA) in the cytoplasm triggers the cGAS-STING signaling pathway." (PMID 38168422, 2023). "However, activation of the cGAS‐STING signaling is usually impaired in multiple types of cancers due to epigenetic hypermethylation." (PMID 37986544, 2023). "Taken together, our findings indicate that GPX4 may be a novel modulator of cancer immunotherapy via activating the cGAS-STING signaling pathway in COAD." (PMID 38065948, 2023). "Notably, the posttranslational modification of cGAS, including ubiquitination, acetylation, and phosphorylation, has been reported to regulate its enzymatic activity in both immune cells and cancer cells." (PMID 37193698, 2023). "Neither irradiation nor cancer generate the usual inflammatory responses in cGAS-STING deficient cells." (PMID 37854446, 2023).
cancer (continued). "In cancer cells, the cGAS-STING pathway is constitutively activated, inducing chronic IFN-β expression, triggered by the accumulation of DNA damage due to replication fork collapse or reactive oxygen species (ROS) that leads to the presence of DNA in the cytoplasm." (PMID 37292941, 2023). "Besides, the activation of the cGAS-STING-CCL5 pathway in mesenchymal stromal cells mediates IR-induced cancer lung metastasis." (PMID 37031183, 2023). "This implies that, whereas in some CIN contexts, cGAS–STING-driven inflammation may help cancer cells survive by counterbalancing the costs of genome instability, in other settings, it explicitly lets them thrive." (PMID 36876871, 2023). "The past few years have seen a shift in our understanding of cGAS–STING signalling in cancer." (PMID 36876871, 2023). "In summary, we have successfully developed a synergy antitumor therapy strategy: nanozymes combined with the cGAS–STING signaling pathway agonist producing oxidative damage-mediated systemic innate immunity to remodel TEM for solid tumor S180 anti-cancer therapy." (PMID 37762239, 2023). "In such a context, chemotherapy treatment, which could trigger cancer DNA double-strand breaks, activated the cGAS-STING pathway and subsequently induced more SLC14A1+CAF formation." (PMID 37079123, 2023). "Furthermore, DNA-containing EVs secreted from topotecan-treated cancer cells have been found to activate dendritic cells and to facilitate antitumor immunity via cGAS-STING signaling." (PMID 36861445, 2023). "Moreover, several cGAS mutants observed in cancer patients fail to inhibit L1 retrotransposition because they disrupt the CHK2-cGAS-TRIM41-ORF2p regulatory axis." (PMID 38086852, 2023). "Indeed, recent evidence instead favours a role for cGAS–STING in the progression of chromosomally unstable cancers." (PMID 36876871, 2023). "Therefore, the therapeutic implications of cGAS-STING pathway modulation should be considered primarily in the context of the interactions between cancer and immune cells." (PMID 38139802, 2023). "Previously, other DNA-damaging agents such as radiation and etoposide have been shown to produce cytosolic DNA and enhance activation of the cGAS-STING pathway in cells, and PARP inhibition upregulates cGAS-STING signaling specifically in HR-deficient cancer cells." (PMID 36976649, 2023). "cGAS-STING plays an important role in necroptotic cell death in cancers." (PMID 38139802, 2023). "The cGAS-STING pathway is therefore of great therapeutic interest: agonists are sought after for use as adjuvant in vaccines or for cancer immunotherapy; while antagonists could be developed as treatment for inflammatory or auto-immune diseases." (PMID 37287967, 2023). "As a result, the cGAS-STING signaling pathway may have important implications in limiting cancer immune escape and metastasis." (PMID 37153627, 2023). "The cGAS-STING pathway has emerged as a crucial pathway in cancer immunology." (PMID 37816954, 2023). "cGAS-STING activity correlates with the inflammatory component of many cancers." (PMID 37854446, 2023). "cGAS-STING-dependent DNA sensing is a double-edged sword for the host to fight against cancer." (PMID 36802409, 2023). "In addition to its well known function in anti-viral immunity, the cGAS-STING-IFN signaling pathway have recently shown to play important roles on cancer and other cellular functions such as DNA repair." (PMID 37833461, 2023). "It is imperative to continue researching the role of lncRNAs in modulating cGAS/STING as their de-regulation may impact cancer patient responses to immunotherapy." (PMID 37370745, 2023). "The role of cGAS/STING agonists in cancer immunity has been widely acknowledged." (PMID 37781382, 2023). "The cGAS-STING pathway serves among other mechanisms in numerous anti-cancer checkpoints." (PMID 38139802, 2023).
cancer (continued). "This drives the production of pro-inflammatory cytokines, rather than IFN-Is following DNA sensing, and thus could be a reason why cancers retain cGAS–STING signalling and subvert it to a different outcome." (PMID 37534795, 2023). "In most scenarios, the activation of cGAS-STING signaling facilitates antitumor immunity; consequently, leveraging the intercellular transmission of cGAS-STING signaling might serve as a promising target for treating cancers." (PMID 36861445, 2023). "Therefore, alternative approaches of cGAS-STING pathway induction for cancer immunotherapy are being sought." (PMID 38022587, 2023). "Thus, functional cGAS-STING signaling pathway promotes survival of cancer cells with CIN in vitro and in vivo." (PMID 36717545, 2023). "The activation of the cGAS/STING pathway in cancer cells seems to have controversial effects." (PMID 37180110, 2023). "Besides the potential association between telomere maintenance machinery and the cGAS-STING pathway, cancer cells actually utilize the cGAS-STING pathway to promote cell-cycle progression." (PMID 35741087, 2022). "Chemotherapy, as a cancer therapy, may induce damaged ssDNA or dsDNA accumulation, which could trigger the signaling pathway of cGAS-STING and enhance T cell response." (PMID 35889509, 2022). "Therefore, gaining an in-depth understanding of the PTM regulatory network of the cGAS-STING signaling axis would be an exciting advance in the fields of cancer immunology and clinical therapy." (PMID 36231006, 2022). "Notably, dysregulation of ISG15 in cancer cells promotes the accumulation of cytosolic DNA, activation of cGAS-STING and chronic induction of type I IFN signaling in a potential auto-inductive loop." (PMID 35681561, 2022). "Furthermore, nuclear cGAS has been shown to promote lethal accumulation of DNA damage in the cancer genome by inhibiting homologous recombination (HR) DNA repair." (PMID 36231006, 2022). "In recent years, due to the activation of cGAS-STING axis can accelerate cancer cell death, and the importance of cGAS-STING axis in regulating cancer immune cycle, many kinds of STING agonists have been developed to activate cGAS-STING pathway to achieve anti-cancer effect." (PMID 35177088, 2022). "However, it is known that the cGAS-mediated immune response is important for the effectiveness of cancer therapy." (PMID 35563740, 2022). "However, when the radiation doses exceed 12–18 Gy, cancer cells induce the DNA exonuclease Trex1 and attenuate the cGAS-STING response by degrading DNA that accumulates in the cytosol upon radiation." (PMID 35741087, 2022). "Our data suggest a further connection between fork protection and the cGAS/STING pathway: that the loss of the cGAS/STING pathway, in addition to its other adaptive advantages, can also benefit cancer cells by severing a link that amplifies NDD and checkpoint activation." (PMID 36710880, 2022). "Its inhibitory effects on cGAS/STING signalling pathway might serve as effective biomarkers for cancer immunotherapy and represent potential therapeutic strategies for NSCLC patients." (PMID 35415876, 2022). "The cGAS-STING pathway playsa promising role in cancer immunotherapy." (PMID 36201304, 2022). "In contrast, cancer cells may benefit from the pro-tumorigenic effects of the cGAS-STING pathway through mtDNA transfer from surrounding cells." (PMID 35741087, 2022). "Notably, the profibrotic effect of cGAS suggests caution regarding the potential harmful effects of targeting cGAS to prevent multiple type of diseases, including inflammatory diseases and cancer." (PMID 35108342, 2022). "Indeed, depletion of cGAS leads to chromosome end-to-end fusion in both human cancer and normal cells." (PMID 34676498, 2022).
cancer (continued). "As a result, the profound mechanism of therapy related inflammation attracted intensive attentions with the aims to better harness TLR, RLR, or cGAS mediated inflammatory responses in combination with the standard treatments to accelerate cancer regression and maximize patient response." (PMID 36588690, 2022). "Likewise, genome instability in cancer cells chronically activates the cytosolic DNA sensor mechanism known as the cyclic GMP–AMP synthase (cGAS)-stimulator of interferon genes (cGAS-STING) pathway." (PMID 35741087, 2022). "Consistent with our findings, a previous study also reported that upregulated cGAS-STING signaling is negatively associated with the infiltration of immune cells and a high level of cGAS-STING signaling predicts a poor prognosis in certain cancers." (PMID 35983076, 2022). "Cancer cells also manage the cGAS-STING pathway when the micronuclei emerge from DNA damage." (PMID 35741087, 2022). "Cancer cells can utilize the cGAS-STING pathway by their telomere maintenance machinery." (PMID 35741087, 2022). "Furthermore, cancer studies found that the classical NF-κB pathway in the cGAS-STING pathway enhances anti-tumor effects by promoting IFN-I expression." (PMID 36741390, 2022). "The cGAS/STING pathway activation contributes to sensitization of cancer cells to radio- and chemotherapy also reviewed in, and to their proliferative capacity; furthermore, STING or cGAS are often mutated or silenced in cancer cells." (PMID 36710880, 2022). "Moreover, the differences in the application of the cGAS pathway-induced senescence in precancerous, early, and advanced cancers deserve further investigation." (PMID 36231006, 2022). "Given the induction of the ssDNA-cGAS-STING pathway in cancer cells cultured in serum-depleted media, it was speculated that the prolonged activation of the cGAS-STING axis in response to the stress of nutrient deprivation may have an impact on cell viability." (PMID 35992877, 2022). "Our findings suggest that cancer cell nuclei might have a diminished ability to respond to the modulating signaling of the mtDNA that occurs via the cGAS-STING pathway." (PMID 35743133, 2022). "cGAS activity regulates various inflammatory diseases and cancer." (PMID 36139387, 2022). "Overall, the cGAS–STING pathway might suppress cancer development by inducing cellular senescence and promoting immune surveillance." (PMID 35734577, 2022). "Interestingly, cancer cells have been shown to down-regulate cGAS and STING expression through hypermethylation of its promoter region in response to the antitumor functions of cGAS-STING signaling." (PMID 35869062, 2022). "Overall, TTFields generate large cytosolic naked micronuclei clusters in GBM and other cancer cell types through focal disruption of the nuclear envelope, thereby recruiting cGAS and AIM2 to create a ripe condition for activation of their cognate inflammasomes." (PMID 35199647, 2022). "This makes cGAS–STING an interesting target for cancer therapy." (PMID 35734577, 2022). "Moreover, transwell co-culturing experiments demonstrated that the presence of CAFs attenuated immune cell infiltration toward cancer cells, but was abolished by activation of cGAS-STING signaling." (PMID 35773436, 2022). "Firstly, PARPi activates cGAS-STING pathway in cancer cells and increases T cell recruitment." (PMID 35062949, 2022). "It is anticipated that the comprehensive pan-cancer analysis could guide cGAS-STING-dependent cancer therapy with better precision." (PMID 35983076, 2022). "cGAS-STING signaling plays a crucial role in regulating various cancer subtypes." (PMID 36139387, 2022). "Notably, up-regulation of this pathway would depend, at least in part, on the presence of an intact cGAS pathway, and cGAS expression levels are often misregulated in cancer." (PMID 35902118, 2022).
cancer (continued). "Together, these results suggest that cGAS protects not only normal cells, but also cancer cells from ionizing radiation, and that cGAS may be a potential target to enhance the radiosensitivity of cancer cells in radiation therapy." (PMID 35563740, 2022). "Also, cGAS can be activated differentially during mitotic errors and later contributes to birth defects, aging, carcinogenesis, and cancer therapy." (PMID 36139387, 2022). "The cGAS-STING pathway is induced by CIN, triggers inflammation and is often deficient in cancer." (PMID 36923311, 2022). "cGAS combined with chromatin for exploiting the genomic instability of cancer cells." (PMID 35346247, 2022). "cGAS-STING pathway in cancer cells could be activated when being infected with engineered vaccinia virus, adenovirus and herpes simplex virus type 1." (PMID 36588690, 2022). "Exploring the relationship between UFMylation modification, cGAS-dependent immune response signaling, and DNA damage repair pathway may provide new targets for cancer prevention and treatment." (PMID 36591232, 2022). "Thus, cancer cells benefit from the cGAS-STING pathway, which is activated by their innate genome instability and DNA damage induced by radiotherapy." (PMID 35741087, 2022). "Both the protection of nascent DNA and the cGAS/STING pathway are often suppressed in cancer." (PMID 36710880, 2022). "The role of cGAS-STING pathway in cancer is quite complicated." (PMID 35978045, 2022). "Furthermore, cancer cells that formed brain metastases expressed cGAMP as a result of cytosolic DNA-mediated cGAS-STING activation." (PMID 36003402, 2022). "The cGAS-cGAMP-STING pathway is an important innate immune signaling cascade responsible for the sensing of abnormal cytosolic double-stranded DNA (dsDNA), which is a hallmark of infection or cancers." (PMID 35928815, 2022). "Next, we assessed the prognostic value of the cGAS-STING sensor for pan-cancer overall survival." (PMID 35983076, 2022). "However, the clinical relevance and prognostic value of the cGAS-STING pathway in human cancers remains largely unexplored." (PMID 35983076, 2022). "Therefore, more works are encouraged to uncover cGAS-driven inflammation microenvironment in different cancer types to enable therapy." (PMID 35983076, 2022). "Furthermore, the cancer cells continuously export cGAMP to the extracellular space when treated with RT, which results in the constitutive activation of the cGAS-STING pathway." (PMID 36139006, 2022). "Quite possibly, this differential requirement for cGAS in fork protection may reflect cancer cells’ adaptive evolution, and/or depend on the degree of activation of the cGAS/STING pathway." (PMID 36710880, 2022). "The cyclic GMP-AMP synthase (cGAS)-stimulator of interferon genes (STING)-mediated senescence-associated secretory phenotype (SASP) pathway has recently been identified in the suppression and promotion of cancers." (PMID 36061145, 2022). "Next, as TOP1 poisons were able to increase micronuclei in cancer cells, we asked whether the cGAS/STING signalling cascade was activated by micronuclei leading to innate immune gene expression, as previously reported in SV40 expressing cells and cancer cells." (PMID 35794238, 2022). "HMGB1 is also associated with senescence, although its role in cGAS/STING-dependent senescence in cancer cells has not been determined." (PMID 33558529, 2021). "In particular, viruses have an intrinsic capability to induce interferons during infection and lysis by triggering pathogen recognition receptors such as cGAS (cyclic GMP-AMP synthase) or RIG-I (retinoic acid-inducible gene I) in cancer cells or adjacent stromal cells." (PMID 33578735, 2021). "It is generally accepted that the cGAS-STING pathway suppresses the development of cancer." (PMID 33720974, 2021).